PROS1 (protein S)
Diseases named in the same sentence as PROS1 in open-access papers (continued):
Sharing a sentence is not in itself a finding about the gene and the disease.
Cirrhosis (14 papers, 2011 to 2025). A chronic disorder of the liver in which liver tissue becomes scarred and is partially replaced by regenerative nodules and fibrotic tissue resulting in loss of liver function. "An acquired deficiency of antithrombotic III, protein C and protein S and the presence of antiphospholipid antibodies are observed in patients with cirrhosis." (PMID 21244669, 2011). "Hypercoagulable states in cirrhosis have been attributed to decrease in the levels of natural anticoagulant proteins (protein C, protein S, and antithrombin III) and increase in factor VIII and von Willebrand factor levels." (PMID 24396346, 2013). "Similarly, anticoagulation factors, including antithrombin, protein C, and protein S, were lower in the cirrhosis patients." (PMID 23555099, 2013). "However, it is unknown whether anticoagulant proteins such as protein C and protein S, which decreased in cirrhosis, influence the PT." (PMID 23555099, 2013).
myocardial infarction (14 papers, 2005 to 2025). Gross necrosis of the myocardium, as a result of interruption of the blood supply to the area, as in coronary thrombosis. "In addition to a familial history of DVT and a history of myocardial infarction, our patient also acquired cardiac mural thrombus and DVT throughout his illness, which increased the suspicion of a protein C, protein S, or antithrombin 3 deficiency." (PMID 39239038, 2024).
gastric cancer (13 papers, 2002 to 2025). A primary or metastatic malignant neoplasm involving the stomach. "In our study, the RP11-328K4.1-hsa-miR-27a-3p-PROS1 regulatory pathway in ICC was detected and can provide ideas and references for the mechanism of action of lncRNA RP11-328K4.1 in gastric cancer." (PMID 31956102, 2020).
hereditary thrombophilia (13 papers, 2004 to 2025). "Hereditary thrombophilia (HT), including the mutation of factor V gene and the deficiency of proteins C, protein S, or antithrombin, is a risk factor for portal vein thrombosis (PVT)." (PMID 32257687, 2020). "Although hypercoagulable states are most often associated with venous thromboses, arterial thromboses are reported in protein C, protein S, antithrombin deficient patients and in those with factor V Leiden, components of hereditary thrombophilia." (PMID 20945813, 2010). "Especially, hereditary thrombophilia, such as low levels of antithrombin, protein C, and protein S, as well as mutations in factors V and II (prothrombin) genes, are associated with thrombotic events in newborns, reflecting an imbalance between coagulants and anticoagulant activity." (PMID 39969648, 2025). "Hereditary thrombophilia caused by mutations in the PROS1 (c.76+2_76+3del) gene is extremely rare." (PMID 39465133, 2024). "In addition, decreased protein S levels tend to increase the risk of thrombus formation.1) In addition, some patients have undetected hereditary thrombophilia." (PMID 36644260, 2022). "Additionally, risk factors of hereditary thrombophilia, including antithrombin III, protein C, protein S, antiphospholipid antibodies, lupus anticoagulant and homocysteine, were evaluated in these 7 APL patients with thrombotic events." (PMID 34130694, 2021).
influenza (13 papers, 2010 to 2025). An acute viral infection of the respiratory tract, occurring in isolated cases, in epidemics, or in pandemics; it is caused by serologically different strains of viruses (influenzaviruses) designated A, B, and C, has a 3-day incubation period, and usually lasts for 3 to 10 days. "Gab1 knockdown in vivo, or LY294002 (a PI3K inhibitor), abolishes the PROS1/AXL-induced protective activity against lethal influenza infection in mice." (PMID 41158072, 2025). "However, the role of PROS1/AXL signaling in influenza A virus (IAV) infection and infection-induced lung injury is largely unknown." (PMID 41158072, 2025). "Unlike enhanced phagocytosis by glucocorticoid–treated human Mph, influenza-induced phagocytosis increase was independent of IL-10 or Mertk/Protein S pathway." (PMID 22238612, 2012).
malaria (13 papers, 2011 to 2024). Malaria is a serious and sometimes fatal disease caused by a parasite that commonly infects a certain type of mosquito which feeds on humans. "Uptake of protein S, prothrombin, and vitronectin was also observed in the blood samples prepared from mice infected with the rodent malaria parasite Plasmodium yoelii, suggesting that similar uptake mechanisms are present among Plasmodium spp." (PMID 32295584, 2020).
nephrotic syndrome (13 papers, 2012 to 2025). A collection of symptoms that include severe edema, proteinuria, and hypoalbuminemia; it is indicative of renal dysfunction. "Nephrotic syndrome, associated with urinary loss of anticoagulantfactors (e.g., antithrombin, protein S), immunomodulatory drug use, high freelight chain levels, and elevated beta-2 microglobulin levels, collectivelyincrease thromboembolic risk." (PMID 40160592, 2025). "Our patient had other VTE risk factors, in addition to the nephrotic syndrome and the COVID-19 infection, namely morbid obesity, PE history and a low functional protein S level." (PMID 34965863, 2021). "Extensive urinary loss of protein S (~ 70 kDa) has also been described in the setting of nephrotic syndrome." (PMID 30651128, 2019). "Thrombotic events are recognized complications of nephrotic syndrome due to antithrombin protein and protein S loss, resulting in hypercoagulable state." (PMID 26858847, 2015). "Finally, nephrotic syndrome itself is a well-known risk factor for thrombosis due to the decreased plasma levels of natural anticoagulants free protein S, C, and antithrombin III, through the urinary loss." (PMID 41246016, 2025). "Acquired protein S deficiency can also be due to oral contraceptive pills or hormone replacement therapy, Pregnancy, oral anticoagulants, DIC, nephrotic syndrome, inflammatory conditions, after an acute thromboembolism, autoantibodies to protein S following varicella, and other infections." (PMID 22567255, 2012).
asthma (12 papers, 2007 to 2026). "Hypothyroidism was present in 3.6% of the cases, while both asthma and protein S deficiency were each observed in 1.8% of the mothers." (PMID 40861757, 2025).
colon carcinoma (12 papers, 2012 to 2025). "Screening results of knockout phenotypes also implied that PROS1 knockout may positively impact lymphocyte-mediated tumour killing in MC38 colon cancer (Kearney2018_T_PD1) models." (PMID 35879775, 2022).
colorectal cancer (12 papers, 2014 to 2025). A primary or metastatic malignant neoplasm that affects the colon or rectum. "Rap2b, a proto-oncogene upregulated in colorectal cancer (CRC), undergoes protein S-palmitoylation at specific C-terminus sites (C176/C177)." (PMID 39277583, 2024).
endothelial dysfunction (12 papers, 2016 to 2025). In vascular diseases, endothelial dysfunction is a systemic pathological state of the endothelium (the inner lining of blood vessels) and can be broadly defined as an imbalance between vasodilating and vasoconstricting substances produced by (or acting on) the endothelium. "It is characterized by thrombocytopenia, endothelial dysfunction, and reduced levels of protein C, protein S, and antithrombin III, increasing the risk of both bleeding and thrombosis." (PMID 40443845, 2025). "Because protein S is produced predominantly in the liver and endothelium, reduced free protein S may result from liver failure or endothelial dysfunction and/or increased consumption." (PMID 28363198, 2017).
hepatocellular carcinoma (12 papers, 2017 to 2025). A malignant tumor that arises from hepatocytes. "Akin to AXL, PROS1 expression was recently found to be inversely correlated to miR-34a in HepG2 hepatoma cells." (PMID 28118606, 2017).
colitis (11 papers, 2016 to 2024). Inflammation of the colon. "This hints that blocking Pros1 in vivo could also result in colitis-induced tumor progression." (PMID 27775650, 2016). "T-cell-specific ablation of Pros1 leads to a significant increase in the percentage of activated dendritic cells producing TNF-α and Interleukin-6 (IL-6) inflammatory cytokines, which, in colitis mouse models, conducts to pathological inflammation." (PMID 27775650, 2016).
pulmonary fibrosis (11 papers, 2017 to 2025). Chronic progressive interstitial lung disorder characterized by the replacement of the lung tissue by connective tissue, leading to progressive dyspnea, respiratory failure, or right heart failure. "MIF has been shown to have anti-fibrotic effects.The overexpression of protein S in lung cells reduces bleomycin-induced pulmonary fibrosis through the interaction between PROS1-AXL and communication with smooth muscle cells." (PMID 37409114, 2023). "Growth arrest-specific 6 (GAS6) and protein S are also vitamin K-dependent proteins, which are important regulators of tissue repair after injury and may be involved in the pathogenesis of pulmonary fibrosis." (PMID 40290659, 2025). "Conversely, the administration of protein S, an alternate ligand binding TAM receptor, has been illustrated to hinder pulmonary fibrosis in mice exposed to bleomycin (BLM) and prevent apoptosis in alveolar epithelial cells." (PMID 38578518, 2024). "On the other hand, an exogenous treatment with protein S, a TAM receptor ligand, significantly decreased the levels of inflammatory and profibrotic markers, decreased lung fibrosis, and blocked apoptosis in alveolar ECs." (PMID 31247991, 2019). "However, the administration of exogenous protein S markedly reduced the levels of inflammatory and profibrotic markers to attenuate BLM-induced lung fibrosis." (PMID 38578518, 2024).
sickle cell disease (11 papers, 2009 to 2026). Sickle cell anemias are chronic hemolytic diseases that may induce three types of acute accidents: severe anemia, severe bacterial infections, and ischemic vasoocclusive accidents (VOA) caused by sickle-shaped red blood cells obstructing small blood vessels and capillaries. "Hypercoagulable states associated with increased levels of eryMPs, such as sickle cell disease and β-thalassemia, are also associated with low levels of protein C and free protein S." (PMID 25136857, 2014). "It has been shown that irreversibly sickled red blood cells and eryMPs can bind protein S and that the red blood cells from sickle cell disease patients support APC-mediated degradation FVa." (PMID 25136857, 2014). "Here, we investigate the contribution of PROS1 and MerTK to the phagocytosis of intact RBC and eryghosts in healthy subjects and patients with sickle cell disease (SCD)." (PMID 41137641, 2026). "In addition, PtdSer‐exposing eryghosts were observed in a higher proportion in the peripheral blood of patients with sickle cell disease (SCD), in which PROS1 levels are frequently decreased." (PMID 41137641, 2026).
autoimmune disease (10 papers, 2019 to 2025). A disorder resulting from loss of function or tissue destruction of an organ or multiple organs, arising from humoral or cellular immune responses of the individual to their own tissue constituents. "The TAM receptor tyrosine kinases (Tyro3, Axl and Mertk) and their ligands (Gas6 and Pros1) play a pivotal role in the resolution of inflammation and have been associated with chronic inflammatory and autoimmune diseases." (PMID 30729671, 2019).
Hypertension (10 papers, 2019 to 2024). The presence of chronic increased pressure in the systemic arterial system. "ProS1 expression was restored by the nutritional intervention, thus suggesting that an impairment of the coagulation cascade, which represents a secondary effect of hypertension, could be ameliorated by a TM-enriched diet." (PMID 36014793, 2022). "There was a statistically significant difference between females with and without hypertension regarding the parameter fibrinogen, D-dimers, Protein S activity, and factor VIII activity." (PMID 36658589, 2023). "In this study, significantly higher protein S levels were found in women with than without hypertension." (PMID 36658589, 2023). "In another study blood protein S levels were higher in relatives of hypertensive men than in men without a family history of hypertension." (PMID 36658589, 2023).
lymphoma (10 papers, 2005 to 2024). A malignant (clonal) proliferation of B- lymphocytes or T- lymphocytes which involves the lymph nodes, bone marrow and/or extranodal sites. "Moreover, there was a trend in genetic variant rs5985 (factor XIII) as a protective factor, and a trend to higher thrombotic risk in patients with factor V Leiden, rs2232698 variant (serpinA10), low total protein S activity, elevated D-dimer, aggressive lymphoma and treatment with dexamethasone." (PMID 38676874, 2024). "Protein S expression was shown in other malignancies like malignant lymphoma, NSCLC and SCLC while only weak expression is shown in others." (PMID 27486820, 2016). "Hypercoagulopathy disorders such as protein C, protein S, and antithrombin III deficiencies were absent in our patient, while treatment with chemotherapeutic agents, endoscopic sclerotherapy, malignant lymphoma, and post-hepatitis B liver cirrhosis were the factors applicable to our patient." (PMID 22799897, 2012).
protein S deficiency (10 papers, 2016 to 2025). "Protein S deficiency is a hematologic disorder characterized by decreased levels or functional impairment of protein S: a vitamin K-dependent glycoprotein integral to the protein C anticoagulant pathway." (PMID 41393758, 2025). "Protein S deficiency is an uncommon prothrombotic disorder characterized by reduced activity of protein S, a plasma serine protease with pivotal and multifaceted roles in coagulation, inflammation, and apoptosis." (PMID 41393758, 2025). "Diagnosis of protein S deficiency is typically established through functional assays, such as clotting-based tests and enzyme-linked immunosorbent assays (ELISA), to assess protein S activity levels." (PMID 41393758, 2025). "Protein S deficiency is an autosomal dominant disorder characterized by a mutation in the PROS1 gene." (PMID 39268299, 2024). "Our group recently identified a disease-causing mutation in the 5′UTR of PROS1 in an extended family affected with protein S deficiency (PSD) and familial thrombophilia." (PMID 35387445, 2022). "Our results were in accordance with other research showing an undetected mutation of the PROS1 gene in up to 50% of individuals with protein S deficiency." (PMID 35815065, 2021). "By utilizing WES, we rapidly identified a previously proven pathogenic variant in the SHBG domain of PROS1, which confirmed the diagnosis of hereditary protein S deficiency." (PMID 34967380, 2021). "Fourth, there is some overlap of free protein S levels between healthy individuals and hereditary protein S deficiency patients with a history of venous thromboembolism." (PMID 35815065, 2021).
protein c deficiency (9 papers, 2014 to 2024). Protein C deficiency is a disorder that increases a person's risk to develop abnormal blood clots due to a deficiency of the Protein C, a protein in the body that prevents blood clotting. "Of all the patients, 32% had protein C deficiency (<70% of activity), 47% had low protein S levels (<65% activity), and 25% had decreased antithrombin III levels (<80% activity)." (PMID 25349733, 2014). "Furthermore their findings showed that Factor V Leiden heterozygosity was present in 5.2%, protein C deficiency in 1.7% and protein S deficiency in 13%, indicating that protein C and protein S levels are lower and higher, respectively, than what we found in our study group." (PMID 26644853, 2015).
schizophrenia (9 papers, 2014 to 2026). A major psychotic disorder characterized by abnormalities in the perception or expression of reality. "These researchers postulated that inflammatory conditions increased the risk of schizophrenia through a combination of mechanisms involving increased SERPINE1 levels or decreased free PROS1 levels." (PMID 29875399, 2018). "This and the 145-fold increased risk of having a first-degree relative with schizophrenia in patients with low free-protein S levels, compared with controls, led us to focus on protein S deficiency." (PMID 26731441, 2016). "Animal studies are very suitable to generate evidence of a direct causal relationship between tPA or protein S and schizophrenia-like symptoms." (PMID 26731441, 2016). "A high prevalence of free-protein S deficiency has been demonstrated in a sample of schizophrenia patients." (PMID 25386352, 2014). "Increasing evidence suggests that disruptions in coagulation pathways—particularly involving t‐PA and protein S—may underlie both neurocognitive impairments and increased thrombotic susceptibility in schizophrenia." (PMID 41510214, 2026). "Last, it suggests future directions for research, such as studies on animal models and on therapeutic approaches for schizophrenia aiming at increasing tPA and protein S activity." (PMID 26731441, 2016). "We recommend that free-protein S levels be assessed in a large series of first-episode drug-naive patients with schizophrenia and their first-degree relatives." (PMID 26731441, 2016). "Next, it analyzes how activity of tPA and protein S is influenced by biochemical abnormalities found in schizophrenia." (PMID 26731441, 2016). "We also recommended that tPA levels, tPA activity, and total- and free-protein S levels be evaluated in animal models of schizophrenia with good etiologic, phenotypic and predictive validity." (PMID 26731441, 2016). "Controlled studies are required to determine how interventions aiming specifically at increasing tPA and protein S activity affect the course of schizophrenia." (PMID 26731441, 2016). "Future research is needed to elucidate the exact role of tPA and protein S in the pathogenesis of schizophrenia and to determine the impact of interventions aiming specifically at correcting activity of tPA and protein S on the course of schizophrenia." (PMID 26731441, 2016). "Next, we point out possible mechanisms by which low activity of tPA and/or protein S might contribute to schizophrenia pathogenesis." (PMID 26731441, 2016). "Low activity of tPA and/or protein S might link different hypotheses for schizophrenia, including the neuropil hypothesis, the NMDA receptor hypothesis, the dopaminergic hypothesis and the hypothesis correlating an adverse fetal environment with an increased risk of developing schizophrenia." (PMID 26731441, 2016). "Biochemical abnormalities commonly found in schizophrenia which may impair tPA and/or protein S activity include hypercortisolemia, increased cytokine levels, hyperhomocysteinemia and antiphospholipid antibodies, such as lupus anticoagulant and IgG and IgM anticardiolipin antibodies." (PMID 26731441, 2016). "None of the controls had free-protein S deficiency and all participants had normal protein C levels, suggesting that protein S could have a role in schizophrenia independent of protein C." (PMID 26593907, 2015). "It should be highlighted that because restoration of hippocampal and prefrontal cortex circuitry in schizophrenia patients requires multiple sequential steps, short-term improvement after normalization of tPA and protein S activity is not expected to occur." (PMID 26731441, 2016).